CD4 (CD4 molecule)
Diseases named in the same sentence as CD4 in open-access papers (continued):
Sharing a sentence is not in itself a finding about the gene and the disease.
prostate carcinoma (continued). "The proliferation of CD4+ T cells in prostate cancer patients before seed implantation was significantly higher than in healthy controls (3.80% mean with 1.61–6.00 95% CI proliferating CD4+ cells in cancer patients versus 1.36% mean with 0.78–1.93% 95% CI in healthy controls)." (PMID 35804830, 2022). "The data also suggest that the insertion of GILT in prostate cancer cells could make them a better target for CD4+ T cells." (PMID 36499557, 2022). "The presence of CD4+ CD25high regulatory T cells (Tregs) in the tumor and blood of cancer patients predicts poor prognosis and Tregs are significantly increased in the bone marrow of patients with prostate cancer that has metastasized to the bone." (PMID 34831167, 2021). "Similarly, following this approach, a MUC1-based autologous dendritic cell (DC) vaccine given to prostate cancer patients was reported to be safe in phase I/II studies and elicited a significant CD4+/CD8+ T cell response." (PMID 33498502, 2021). "Similarly, ICB-resistant prostate cancer that is metastatic to bone was shown to regress in combination with TGFβ inhibition due to increased Th1 CD4+ and CD8+ T cells." (PMID 34789823, 2021). "In the single prostate cancer study, increased pre- and post-RT viral load was associated with increased risk of biochemical failure, but decreased CD4 count was not." (PMID 30105217, 2018). "Similarly, CD4+Foxp3+Treg cells were also higher in prostate cancer bearing mice and glioma tumor bearing mice." (PMID 23587428, 2013). "Since PSCA-derived peptides were reported to be a target of T-cell-based immunotherapy for advanced prostate cancer, the shorter PSCA protein would cause the activation of CD4-positive and/or CD8-positive T cells and subsequently promote epithelial mucosal injury." (PMID 23704932, 2013). "For metastatic castration-resistant prostate cancer, a disease which continues to have a poor prognosis, we show that female lymphocytes, particularly CD4 T cells, adoptively transferred into prostate-cancer challenged male mice can mediate substantial anti-tumor effects." (PMID 22493742, 2012). "In a phase I study of a DNA vaccine encoding PAP in 22 patients with castration-sensitive prostate cancer, 41% of patients developed PAP-specific CD4+ and/or CD8+ T-cell proliferation, and 14% developed PAP-specific IFN-γ-secreting CD8+ T cells by ELISPOT assay." (PMID 24213505, 2012). "The results of the present study show that the presence of an increase in CD4+ T-lymphocyte infiltrate was associated with poor cancer specific survival, independent of stage, in patients with prostate cancer." (PMID 15266325, 2004). "In summary, the results of the present study have shown that the presence of increased CD4+ T-lymphocyte infiltration within the tumour was associated with poor outcome, independent of stage, in patients with prostate cancer." (PMID 15266325, 2004). "Similarly, another study that also found increased NSD2 expression with prostate cancer progression demonstrated that high NSD2 expression was positively correlated with the infiltration level of CD4+tumor-infiltrating lymphocytes (TILs) and negatively correlated with that of CD8+TILs." (PMID 40586874, 2025). "Results from CWR22Rv1 xenografted orthotopic mice where cultured CD4+ T lymphocytic cell lines HH and Molt-3 were co-implanted into the anterior prostate and showed a significantly higher metastasis rate in the diaphragm as compared to the prostate cancer cell control group." (PMID 36836690, 2023). "Men with abundant CD163+ M2 macrophages in prostate tissue have a higher risk of lethal prostate cancer and the interpretation is that the presence of these suppressor cells, CD163+ M2 macrophages, and CD4+ FoxP3+ Tregs may promote an immunosuppressive microenvironment." (PMID 35326519, 2022).
prostate carcinoma (continued). "Furthermore, we describe here associations indicating that patients with Alzheimer’s disease might primarily be affected with LOY in NK cells, while men diagnosed with prostate cancer appears to more frequently display LOY in CD4 + T cells and granulocytes." (PMID 33837451, 2021). "Indeed, in an oncogene-induced model of prostate cancer in mice, attenuation of TGF-β signalling in T cells resulting from expression of the Cd4-Tgfbr2dn transgene was associated with increased infiltration of tumors by CD4 and CD8 T cells expressing high levels of IFNγ and Gzmb." (PMID 34302795, 2021). "In addition to Tregs, another subset of CD4+ T cells, Th17 cells, may affect prostate cancer biology and responses to immunotherapy." (PMID 28292326, 2017). "Our data correlating CXCL16 and CXCR6 with stage and grade of prostate cancer provide additional evidence that, in the prostate, inflammation is tumorigenic, and should stimulate the increasing interest in a possible tumor-promoting role specifically for CD4+ T cells." (PMID 19690611, 2009). "Whereas contrasting prognoses have been reported concerning CD8+ T cell infiltration in prostate cancer, the synergistic effect of CD8+ and CD4+ T cells remains less explored." (PMID 41534468, 2026). "T cell subsets, including central memory CD4 T cells and effector memory CD8 T cells, exhibit heterogeneity in prostate cancer." (PMID 41343534, 2025). "Comparative analysis revealed that compared with pre-chemotherapy levels, there was an increase in the numbers of CD3 + and CD3 + CD4 + cells, the CD4 +/CD8 + ratio, and the number of NK cells in prostate cancer patients." (PMID 41413917, 2025). "In prostate carcinoma, LTBP2 protein increases in parallel with CD4+ T-cell infiltration and immune checkpoint blockade." (PMID 39201614, 2024). "The CD4+CD25+ subset of T cells known as regulatory T cells, when present at higher levels in tumor tissue and peripheral blood of men with prostate cancer appear to promote cancer progression." (PMID 38523528, 2024). "To meet this objective, we evaluated the levels of CD3+, CD4+ T‐cell lymphocytes, and CD20+ B‐cell lymphocytes in prostate cancer patients pre‐ and post‐malignancy." (PMID 38523528, 2024). "In prostate cancer, CD8+, CD4+ and FoxP3+ cells have been shown to be more common in malignant regions compared to benign regions." (PMID 39602457, 2024). "We demonstrated an abundant immune cell infiltrate within the prostate cancer TME, dominated by CD68+ cells, with substantial numbers of CD8+ and CD4+ T cells." (PMID 39602457, 2024). "LPA1 expression is positively correlated with the infiltration of immune cells, including CD4+ and CD8+ T cells, NK cells, and dendritic cells, leading to improved OS in prostate cancer." (PMID 37749552, 2023). "In patients with prostate cancer, a SLP vaccine containing CD4+ T cell helper epitopes can induce both CD4+ and CD8+ T cell responses." (PMID 37829505, 2023). "Enhanced tumor infiltration of CD3+CD4+, CD3+CD8+ T cells and NK cells were observed in the Myc-dependent prostate cancer (MycCaP) tissues after small molecule inhibitors (MYCi) treatment." (PMID 36119473, 2022). "A similar effect of androgen deprivation on T cell development and differentiation has been observed in prostate cancer patients, with an expansion of RTE and naive T cells, particularly among CD4+ cells." (PMID 35351135, 2022). "Here, we showed that the insertion of GILT into prostate cancer cells enhanced PSMA processing and presentation via the HLA class II pathway with an increased CD4+ T cell recognition of prostate cancer cells." (PMID 36499557, 2022). "Prostate cancer patients treated with carbon ion radiotherapy (CIR) experienced a gradual decrease of CD19+ cells and an increase of CD4+ cells during RT." (PMID 35719968, 2022).
prostate carcinoma (continued). "In a mouse model of prostate cancer (TRAMP C-2), the pharmacological inhibition of WHSC1 reduced the infiltration of CD4+CD25+ Tregs and upregulated MHC-II expression on CD45+CD11c+ DCs." (PMID 35892678, 2022). "We found a similar pattern of expression of LILRB4 in the TRAMP-C2 prostate cancer model, where the expression of LILRB4 was higher on CD4+ T cells than on CD8+ T cells." (PMID 33974041, 2021). "We found that lymphocyte subset such as CD3+, CD4+, CD19+, CD4/CD8 ratio predict prostate cancer patients’ short-term efficacy and toxicity with CIRT." (PMID 34804961, 2021). "Data from the Sharma laboratory in both preclinical models as well as patients with bladder cancer, prostate cancer, and metastatic melanoma suggested that increased ICOS protein expression on CD4+ T cells was indicative of a response to CTLA-4 treatment." (PMID 33594075, 2021). "The other chemokine receptor gene whose expression correlated with that of CXCR4 was CX3CR1, which is expressed in NK cells, subsets of monocytes, CD4+ and CD8+ T cells, as well as prostate cancer and various experimental cancers and cancer cell lines." (PMID 29088715, 2017). "In the epithelial compartment of tumors from 535 prostate cancer patients, 50, 44 and 58% had high immune-infiltration for CD3, CD4 and CD8, respectively." (PMID 28428880, 2017). "FOXP3+CD25+CD4+ Tregs are known suppressors of CD8+ cytotoxic T cells, and are observed up-regulated in multiple cancer types, including prostate cancer." (PMID 28460462, 2017). "Variation in number of CD4+ cells, the CD4/CD8 ratio, and number of CD19+ cells after CIR was observed in all 19 prostate cancer patients." (PMID 27029063, 2016). "Using mouse models, investigators have described the essential collaboration that is required between CD4+ and CD8+ TIL subsets in order to mediate anti-tumor responses against prostate cancers." (PMID 25901284, 2015). "In other study with prostate cancer patients, immunization led to recruitment of CD1a+ DCs, CD68+ macrophages, eosinophils, and neutrophils 4 days following inoculation; CD4+ and CD8+ cell affluence increased with immunizations." (PMID 25870600, 2015). "The aim of the present study was to examine the relationship between CD4+ and CD8+ T-lymphocyte infiltration and survival in patients with prostate cancer." (PMID 15266325, 2004). "Furthermore, HLA-II-restricted prostate cancer-specific epitopes were included in the TENDU vaccine constructs as strong and long-lived CD8+ T cell responses are dependent on CD4+ T cells." (PMID 40520577, 2025). "On the other hand, the presence of similar collections of CD4(+) and CD8(+) T cells in our Cdk12-null mouse prostate cancer model suggests other factors (such as increased proinflammatory signaling) might also be in play." (PMID 40504161, 2025). "Previous studies show that LOY in circulating leukocytes of aging men was associated with shorter survival and non-hematological cancer, as well as higher LOY in CD4 + T-lymphocytes in men with prostate cancer vs. controls." (PMID 38658633, 2024). "Moreover, in prostate cancer, CSCs secrete tenascin-C to hinder the activation and proliferation of CD8+ and CD4+ T cells through interaction with α5β1 integrin located on T cells." (PMID 39671359, 2024). "Similarly, NCTD treatment can decrease the number of tumor-infiltrating Tregs and increase the number of CD4+ and CD8+ T cells in prostate cancer cells." (PMID 37895943, 2023). "Furthermore, chemokine CXCL9 secreted by the prostate cancer cells was shown to mediate CD4+ T cell recruitment to the prostate cancer regions, and CXCL9 blockage suppressed CD4+T cell migration towards the prostate cancer cells." (PMID 36836690, 2023). "Proper CD4+ stimulation requires efficient HLA class II Ag presentation by both professional and nonprofessional APCs, including prostate cancers themselves." (PMID 36499557, 2022).
prostate carcinoma (continued). "Given the complexity of T cells, and considering that the impact of aging on T cell responsiveness is different among various T-cell subsets, it is crucial to define how T subset responses (CD4 and CD8 T cells) in the aging process promote or inhibit prostate cancer." (PMID 36358603, 2022). "Not surprisingly, GILT is almost completely absent from cancer cells, including prostate cancer, contributing to the poor processing and presentation of endogenous Ags for CD4+ T cell stimulation." (PMID 36499557, 2022). "Prostate cancer has a low number of tumor-infiltrating lymphocytes, although with a predominance of CD4+ Tregs and M2 macrophages as opposed to CD8+ T lymphocytes and natural killer (NK) cells." (PMID 35327339, 2022). "Alteration in the CD4+ T cell pool was most probably related to the development of the malignant condition itself since prostate cancer patients had a mildly reduced CD4+ T cell pool which was not significantly influenced by LDR brachytherapy." (PMID 35804830, 2022). "In addition, while regulatory T cells are typically identified as CD4 + CD25 + FoxP3+ T cells, it has been shown that both CD4 + CD25+ and CD8 + FoxP3+ regulatory T-cell populations can be found within prostate cancer tumors." (PMID 33820953, 2021). "At the same time, treatment with ipilimumab has been shown to upregulate expression of PD-L1 and V-domain immnunoglobulin suppressor of T-cell activation in CD4+ T cells, CD8+ T cells, and CD68+ macrophages within prostate cancer tissue samples compared to untreated samples." (PMID 33820953, 2021). "Indeed, ADT induces prostate cancer infiltration by immune cells, predominantly characterized as CD3+, CD4+, and CD8+ T cells and CD68+ macrophages." (PMID 33284790, 2020). "However, in a murine preclinical model of prostate cancer, mice who received GVAX prior to anti-CTLA-4 demonstrated increased CD8+ and CD4+ T cells compared to those who received anti-CTLA-4 treatment first." (PMID 33019493, 2020). "In addition, upregulation of human leukocyte antigen (HLA)-DR on CD4+ and CD8+ T cells induced by combined immunotherapy with GVAX and ipilimumab of patients with advanced prostate cancer has also been reported." (PMID 29494517, 2018). "Our results demonstrate that the CD4/CD8 ratio and CD19+ cell counts were higher in the PR+CR group than in the SD group, suggesting that stronger immune status predicts the short-term efficacy of prostate cancer patients treated with carbon ions." (PMID 27029063, 2016). "The immune system in NOD/SCID/IL-2Rγnull (NSG) mice was reconstituted by the co-administration of human peripheral blood lymphocytes (PBL) or subsets (CD4+ or CD8+) and autologous human dendritic cells (DC), and animals simultaneously challenged by implanting human prostate cancer cells (PC3 line)." (PMID 25901284, 2015). "Flow cytometry analysis of peripheral blood obtained from prostate cancer patients and healthy donors revealed that the percentage of CD4+CD25highFoxP3+ Tregs was not significantly different between the 2 groups." (PMID 24213505, 2012). "CD4+ and CD8+ T cells are detectable in prostate glands of men with prostate cancer supporting the assumption that prostate cancer might be a good candidate for immunotherapy." (PMID 21197271, 2010). "Furthermore, immune classification based on NSD2 expression and CD4+ TILs and CD8+ TILs was used to stratify prostate cancer patients based on prostate-specific antigen overall survival and showed that increased NSD2 expression was predictive of reduced overall survival." (PMID 40586874, 2025). "Given the lack of GILT expression in prostate cancer, cysteinylated peptides would not be reduced and presented to CD4+ T cells displaying an altered, nonfunctional peptide that could induce T cell tolerance." (PMID 36499557, 2022).
prostate carcinoma (continued). "Accordingly, immune suppression may increase the risk of tumor growth, relapse and metastasis Thus, we speculated that the number of CD3+, CD4+ cells, CD4/CD8 ratio, and circulating CD19+ lymphocytes could be used to assess prostate cancer progress and prognosis." (PMID 27029063, 2016). "Taken together, these results suggest that GILT has the potential to increase HLA class II Ag presentation and CD4+ T cell recognition of prostate cancer cells, and GILT-expressing prostate cancer cells could be used in designing cell therapy and/or vaccines against prostate cancer." (PMID 36499557, 2022). "A subset of five flow cytometry features was selected (CD8+CD45RA−CD27−CD28−; CD4+CD45RA−CD27−CD28−; CD4+CD45RA+CD27−CD28−; CD3−CD19+; CD3+CD56+CD8+CD4+) from a set of 20 features, which could potentially discriminate between the presence of benign disease and prostate cancer." (PMID 29326690, 2017). "Lastly, unique hub-genes of naive CD4+ T-cells, such as HSPA8, are reported to be expressed in CD8+ T-cells in prostate cancer, while UBC, UBB, CTNNB1, and H3-3B are not reported, rendering them novel markers for naive CD4+ T-cells." (PMID 40906153, 2025). "Mogamulizumab reduced circulating CD4+Foxp3+ Tregs and CCR4+ Tregs but not CD8+ cytotoxic T cells and CD4+ helper T cells in dogs with prostate cancer." (PMID 35131860, 2022). "As a group, these patients with prostate cancer had a significantly decreased percentage of ζ-positive CD3+ and ζ-positive CD4+ T cells, but not of the CD8+ T cells, when compared to normal donors." (PMID 11870501, 2002).